EGFR (epidermal growth factor receptor)
Diseases named in the same sentence as EGFR in open-access papers (continued):
Sharing a sentence is not in itself a finding about the gene and the disease.
squamous cell carcinoma (continued). "Moreover, in squamous carcinoma both the over expression of Bcl-2 or EGFR activation induced EMT, promoting cell migration and invasion via the ERK1/2 and PI3K-regulated MMP-9/E-cadherin signaling pathways." (PMID 25277187, 2014). "In the case of squamous cell carcinoma, E-cadherin-mediated cell-cell adhesion was found to induce epidermal growth factor receptor (EGFR) activation, which triggers the ERK/MAPK signaling module and further blocks down-regulation of the anti-apoptotic protein Bcl-2, promoting tumor cell survival." (PMID 24797520, 2014). "Treatment of human squamous cell carcinoma A431 which overexpresses epidermal growth factor receptor (EGFr) in subcutaneous murine xenografts with anti-EGFr antibodies conjugated to 15 nm AuNPs and NIR resulted in complete tumor ablation in most cases with virtually no normal tissue damage." (PMID 24520385, 2014). "The ability of SST0116CL1 to downregulate the expression of a few representative Hsp90 protein clients and to induce the expression of Hsp70 protein was assessed, by western blot analysis, in the A431 human squamous carcinoma cell line, characterized by the constitutive overexpression of EGFR." (PMID 25096516, 2014). "In addition, we showed that Y845 phosphorylation also occurs in A431 epidermoid carcinoma cells, where a fraction of EGFR and Src constitutes a physical complex via the activation segment of Src that we called the inter-DFG-APE region." (PMID 23702846, 2013). "A previous study conducted in Italy found no EGFR mutations among 454 patients with squamous cell carcinoma." (PMID 23468851, 2013). "The frequency of EGFR mutations, either in exon 19 or exon 21, was higher in women than in men (p=0.015; p<0.0005), in adenocarcinoma than in squamous cell carcinoma (p<0.0005; p<0.0005), and in the non-smokers than in smokers (p=0.031; p=0.002)." (PMID 24205245, 2013). "In order to evaluate the binding specificity and affinity of cytoplasmically expressed sdAbs to human EGFR, two dimensional cell cultures of epidermoid carcinoma (A431), squamous carcinoma (FaDu) and ductal carcinoma (MDA-MB 435S) cells were incubated with radiolabeled sdAbs." (PMID 24161153, 2013). "Most notably squamous cell carcinomas are mostly commonly associated with smoking history and are marked by amplification of PIK3CA and p63; whereas adenocarcinomas are associated with a high frequency of mutations in KRas and EGFR." (PMID 24123619, 2013). "And in the remaining 17 non-adenocarcinoma cases, only one had an EGFR mutation, and it occurred in a female patient with squamous cell carcinoma." (PMID 23590575, 2013). "Furthermore, rab31 was shown to modulate epidermal growth factor receptor (EGFR) internalization in the epidermoid carcinoma cell line A431." (PMID 22920728, 2012). "EGFR mutations are relatively rare (<3.6%) in squamous cell carcinoma and EGFR testing is not routinely recommended per NCCN guidelines." (PMID 22363766, 2012). "Based on these observations, we hypothesized that C225 can enhance cytotoxicity with the PARPi ABT-888 in UM-SCC1, UM-SCC6, and FaDu cells, which are well characterized, EGFR overexpressing, representative squamous cell carcinoma of the head and neck." (PMID 21912620, 2011). "Clinical studies have demonstrated that erlotinib is effective even in patients who are not considered to be good responders to gefitinib, such as those with a negative EGFR mutation, squamous cell carcinoma, or a history of smoking." (PMID 21194487, 2011). "We showed EGFR expression in 20 out of 24 cases (83.3%) of squamous cell carcinoma of the tonsils." (PMID 20459770, 2010). "EGFR status in anal canal and tonsil squamous cell carcinoma." (PMID 20459770, 2010). "Downregulation of CIP-4 expression in A431 epidermoid carcinoma cells causes elevation of EGFR but, surprisingly, does not affect surface expression of EGFR." (PMID 21143914, 2010).
squamous cell carcinoma (continued). "In our study, no EGFR mutations were found in tonsil squamous cell carcinoma, which confirms that EGFR kinase mutations are rare in Caucasian patients." (PMID 20459770, 2010). "We can state that EGFR mutations were absent from squamous cell carcinoma of the anus and tonsils, but that EGFR protein expression was detected in the majority of the cases." (PMID 20459770, 2010). "The epidermal growth factor receptor (EGFR) cascade has been shown to be involved in mucin production and goblet cell hyperplasia, repair of damaged epithelium, as well as development of squamous cell carcinoma." (PMID 18039368, 2007). "No EGFR mutations were found in any of the patients with squamous carcinoma or large cell carcinoma." (PMID 17060940, 2006). "Our initial results indicate that this new generation of antibodies which bind with high affinity to the EGFR, block growth factor-receptor interaction and inhibit the growth of human squamous carcinoma cell lines overexpressing the receptor have potential for clinical application." (PMID 8094290, 1993). "Importantly, no cases with squamous cell carcinoma, small cell lung cancer, or large cell neuroendocrine carcinoma tested positive for EGFR mutations." (PMID 39429333, 2024). "The EGFR mutation rate was increased in patients with adenocarcinoma compared with that in patient with squamous carcinoma, and in non-smoking patients compared with that in smoking patients, and the differences were statistically significant (p<0.05) (Table-III)." (PMID 39634906, 2024). "While EGFR inhibitors have shown limited effects in patients that were not pre-selected according to molecular subtype, other reports suggested that EGFR targeting might be particularly efficient in the basal/squamous cell carcinoma-like BC subtype." (PMID 38672614, 2024). "Thus, our studies in squamous carcinoma propose that genomic imbalances related to the EGFR and MAP3K1 may be an important factor in resistance to PDT." (PMID 39766391, 2024). "Indeed, in vitro models using aggregates of squamous carcinoma cells grown in a nutrient-deprived suspension, have been shown to arrest via growth factor-independent epidermal growth factor receptor (EGFR)-Y1086 autophosphorylation, which leads to reduced AKT signalling and reduced CyclinD." (PMID 37608096, 2023). "However, the majority of those who overexpressed EGFR presented with late-stage disease, squamous cell carcinoma were younger, which may play a part in the poorer survival in this cohort of patients." (PMID 38414930, 2023). "But squamous cell carcinoma cases showed no mutation for the EGFR exon 21 genotype." (PMID 38008767, 2023). "As there is essentially no need to confirm EGFR mutation in squamous cell carcinoma, the EGFR mutation status of many of the cases (18/42, 42.8%) remains unknown." (PMID 35135489, 2022). "In squamous cell carcinomas (SCCs), the SCC-specific SE region co-occupied by TP63 and SOX2 enhances seRNA CCAT1 (colon cancer associated transcript 1) transcription, and the TP63/SOX2/CCAT1 complex promotes tumorigenesis by activating EGFR (epidermal growth factor receptor) transcription." (PMID 35461306, 2022). "In addition, pleural endothelium samples were positive for EGFR in squamous cell carcinoma samples." (PMID 34680445, 2021). "Furthermore, patients with adenocarcinoma and EGFR mutations showed a longer overall survival than did patients with squamous cell carcinoma and without EGFR mutation (p=0.021 and p=0.038, respectively)." (PMID 33787673, 2021). "Therefore, we investigated whether external factors like blood serum can affect squamous carcinoma cell growth and response to EGFR-targeted drugs." (PMID 33748471, 2021).
squamous cell carcinoma (continued). "EGFR mutation (EGFRm) testing is recommended in all patients with advanced non-squamous cell carcinoma, it is not recommended in patients with an unequivocal diagnosis of squamous cell carcinoma with the exception of never/former light smokers (< 15 pack years)." (PMID 33210237, 2021). "Furthermore, α5β1 was capable of triggering pro-survival signaling on epidermoid carcinoma cells, thereby regulating cell proliferation through both a constant activation of the Akt kinase, an apoptosis suppressor, and the Epidermal Growth Factor Receptor (EGFR)." (PMID 33916607, 2021). "A similar study involving EGFR mutation in epidermoid carcinoma showed that treatment of EGFR‐driven tumor cells with canertinib and dacomitinib, but not with anti‐EGFR antibody (cetuximab) or etoposide, increased the release of exosome‐like EVs containing EGFR and gDNA." (PMID 32767659, 2021). "Similarly to the uncertain clinical efficacy of EGFR-tyrosine kinase inhibitor in squamous cell carcinoma, it is also controversy whether ALK rearrangement squamous cell carcinoma patients could benefit from ALK inhibitor." (PMID 32727606, 2020). "Clinical guidelines recommend routine mutation testing and identification of EGFR mutations in all patients with NSCLC of non-squamous cell carcinoma (non-SCC) histology to identify who may benefit from approved EGFR-TKIs." (PMID 32345265, 2020). "Together, our results show that EGFR-MBs and ultrasound treatment increases the efficacy and specificity of intracellular drug uptake, suggesting this could be a novel drug-targeting modality for oral squamous cell carcinoma chemotherapy treatment." (PMID 28938010, 2017). "Furthermore, EGFR-TKIs are also effective in cases of squamous cell carcinoma that commonly do not show the EGFR gene mutation." (PMID 27070423, 2016). "Furthermore, the activating EGFR mutations are more commonly observed in patients with non-squamous cell carcinoma and no prior history of smoking, as well as in females and those of Asian descent." (PMID 25061601, 2014). "However, the EGFR mutation rates in the patients who underwent Neoadj-Chemo dropped to 33.3% (9/27) in adenocarcinoma and 8.57% (3/35) in squamous cell carcinoma, with a non-significant difference (P>0.05)." (PMID 23520442, 2013). "The NCCN guidelines do not recommend EGFR mutation testing in squamous cell carcinoma." (PMID 23468851, 2013). "However, in some other studies, the mean level of EGFR amounts was more in squamous cell carcinoma." (PMID 23133538, 2012). "However, in squamous carcinoma A431 cells, which express high levels of endogenous EGFR, EGF at pM range stimulates cell growth, while at nM range inhibits proliferation, arrests cell cycle, alters cdk2 activity by induction of p21, and even induces cell apoptosis." (PMID 22927910, 2012). "No EGFR mutations were detected in 17 squamous cell carcinomas between May 2009 and February 2010; mutation analysis was subsequently performed only in patients diagnosed with NSCLC non-squamous histology." (PMID 21949883, 2011). "We examine the potential prognostic and predictive roles of EGFR variant III mutation, EGFR gene copy number (GCN), human papillomavirus (HPV) infection, c-MET and p16INK4A protein expression in recurrent or metastatic squamous cell carcinoma of the head and neck (R/M SCCHN)." (PMID 21352589, 2011). "No prior study has investigated EGFR gene mutation status in squamous cell carcinoma of the anus." (PMID 20459770, 2010). "Such are the alterations in BRAF, epidermal growth factor receptor (EGFR) gene, anaplastic lymphoma kinase (ALK) gene, Kirsten Rat Sarcoma virus (KRAS), repressor of silencing 1 (ROS-1) and PD-L1 for squamous cell carcinoma." (PMID 41153394, 2025).
squamous cell carcinoma (continued). "The transcription factor Slug represses E-cadherin expression and induces EMT in several cancers 68, while EGFR/MAPK signaling promotes CSC function in colorectal, breast, and squamous cell carcinoma 69-71." (PMID 39781447, 2025). "Some studies in basal cell carcinoma (BCC) and squamous cell carcinoma (SCC) report CCL27 downregulation via Fas and epidermal growth factor receptor (EGFR) signaling to evade immunity." (PMID 41050670, 2025). "BM, brain metastases; Ns‐NSCLC, non‐squamous non‐small cell lung cancer; SCC, squamous carcinoma; SCLC, small cell lung cancer; EGFR, epidermal growth factor receptor." (PMID 40719284, 2025). "A431 cells, derived from a human epidermoid carcinoma (a type of SCC), are widely used as a model for skin cancer and epidermal growth factor receptor (EGFR)-targeted studies due to their high EGFR expression." (PMID 40872202, 2025). "Given the histopathological similarities between KA and squamous cell carcinoma (SCC), therapeutic strategies involving epidermal growth factor receptor (EGFR) inhibitors (e.g., cetuximab) or immune checkpoint inhibitors (e.g., cemiplimab) appear rational." (PMID 39205234, 2024). "We investigated UTMC-mediated delivery of siRNA directed against epidermal growth factor receptor (EGFR), to squamous cell carcinoma (SCC) via a novel MB-liposome complex (LPX)." (PMID 38577322, 2024). "Based on the results of the postoperative pathology, the patients were divided into benign/malignant groups, adenocarcinoma (AC)/squamous carcinoma (SCC) groups, and EGFR-positive (EGFR+)/EGFR-negative (EGFR-) groups." (PMID 38730287, 2024). "Resistance to EGFR-TKIs can also lead to changes in the EGFR genetic profile, histological transformation into SCLC or squamous cell carcinoma, and alterations in the tumor immune microenvironment and programmed death-ligand 1 (PD-L1) expression." (PMID 39682183, 2024). "A study of 320 surgical NSCLC tissues revealed that adenocarcinomas, especially epidermal growth factor receptor (EGFR) mutants, had higher expression of FRα compared to squamous-cell carcinomas." (PMID 38256120, 2024). "In squamous cell carcinoma, activation of TLR4 reversed cetuximab-induced inhibition of proliferation, migration and invasion, increasing resistance to anti-EGFR therapy." (PMID 38067326, 2023). "We used one commercial EGFR expressing cell lines as target cells, the UM-SCC-2A squamous cell carcinoma of the oral cavity and autologous primary tumor cells." (PMID 36341402, 2022). "ICR scid mice were injected with GBM and epidermoid carcinoma cell lines that displayed high (A431 and U87EGFR cells) or low (TS895 and U87) EGFR expression." (PMID 35145836, 2022). "Concerning histology, squamous cell carcinoma (SCC) was diagnosed in 324 (60.8%) patients and among 184 (34.5%) nonsquamous NSCLC patients, 38 (20.7%) patients carried mutant EGFR." (PMID 34927371, 2022). "The high numbers of MYC and EGFR variations in PSCC are in concordance with previous evidence reported in head and neck cancers squamous cell carcinoma, a similar tumor with dual pathogenesis." (PMID 35008677, 2021). "A431 cells are deviated from squamous carcinoma (ATCC: CRL: 1555) and express the epidermal growth factor receptor (EGFR)." (PMID 34445651, 2021). "Compared with adenocarcinoma, squamous cell carcinoma showed strong communications with endothelial by the MIF/TNFRSF10D, EGFR/GRN, EGFR/HBEGF, and EPHB2/EFNB2 interactions." (PMID 34185421, 2021). "The EDF genes specific for the histology subtype also include TSHR, KEAP1, and EGFR in adenocarcinoma, and NOTCH1, PIK3CA in squamous cell carcinoma." (PMID 33078899, 2020). "EGFR mRNA expression was measured in serum at baseline and after treatment in 247 Adenocarcinoma (ADC) and 103 Squamous cell carcinoma (SCC) subjects." (PMID 33247670, 2020). "In the setting of acquired EGFR TKI resistance, phenotypic transformation encompasses EMT, SCLC, and transformation to squamous cell carcinoma (AST)." (PMID 32292420, 2020).
squamous cell carcinoma (continued). "NSCLC samples included 81 (17%) EGFR-positive, 37 (8%) ALK-positive, and 91 (19%) squamous-cell carcinoma specimens." (PMID 32127616, 2020). "They recommend systematic biomarker/molecular testing including PDL1, EGFR, ALK, ROS1, and BRAF for all non-squamous cell carcinomas." (PMID 33704175, 2020). "Combination of IPA-3 or OTSSP167 and auranofin was highly synergistic in EGFR or KRAS mutant adenocarcinoma and squamous cell carcinoma cell lines and decreased tumor volume in mice models." (PMID 31660987, 2019). "AG1478, a specific epidermal growth factor receptor (EGFR) inhibitor, augments oridonin-induced apoptosis through oxidative stress and mitochondrial pathways in human epidermoid carcinoma A-431 cells." (PMID 31719837, 2019). "This is in line with observation of Zuo et al49 who showed that pharmacologic inhibition of EGFR activity reduced the production of MMP‐9, as well as squamous carcinoma cell migration and invasion." (PMID 31638339, 2019). "Notably, a compound EGFR mutation was detected in four non-adenocarcinoma patients, including two squamous cell carcinomas (SCC, L858R + L858Q and L858R + T790M), one lymphoepithelioma-like carcinoma (LELC, 19Del + L858R) and one adenosquamous carcinoma (ASC, 19Del + T790M)." (PMID 30055651, 2018). "Two cell lines expressed high levels of EGFR (human squamous carcinoma cell line A431, and HEK-293/EGFR stable cell line) and one cell line (HEK-293) expressed relatively low levels." (PMID 30135446, 2018). "In contrast to hydrogen peroxide-induced EGFR activation, the addition of EGF to human epidermoid carcinoma A431 cells, which highly express the EGFR, leads to increased levels of intracellular ROS, especially hydrogen peroxide." (PMID 29548337, 2018). "Specifically, G. tsugae methanol extract was shown to inhibit epidermal growth factor receptor (EGFR) and VEGF, which are important for tumor angiogenesis and growth in human epidermoid carcinoma cells in vitro and in vivo." (PMID 29872510, 2018). "In this study, we developed an anti-EGFR antibody-conjugated MB (EGFR-MB) as a targeting agent and investigated the efficacy of BLM delivery using sonoporation with EGFR-MBs in vitro and in vivo in a squamous cell carcinoma model." (PMID 28938010, 2017). "In primary tumors, higher PD-L1 positivity was observed in squamous cell carcinoma (SCC) and wild-type EGFR than in adenocarcinoma and mutant EGFR, respectively (adenocarcinoma, 13.5% vs. 5.4%, P = 0.005; mutant EGFR, 18.9% vs. 0% P = 0.05)." (PMID 29152077, 2017). "In squamous cell carcinoma (SCC) cells Axl has been shown to dimerize with EGFR and promote ligand independent phosphorylation of EGFR, leading to increased activation of phospholipase Cγ (PLC γ) and protein kinase C ζ (PKCζ), as well as mTOR." (PMID 27611946, 2017). "The current standard of care calls for EGFR sequencing in all advanced-stage (stage IV and recurrence) patients with NSCLC of all histological subtypes, except for squamous cell carcinoma." (PMID 28558785, 2017). "However, consistent with our results, other studies could not detect any EGFR mutations in squamous cell carcinoma." (PMID 28832323, 2017). "EGFR testing in NSCLC was recommended for all newly diagnosed patients with advanced NSCLC of all histological subtypes, except for squamous cell carcinoma." (PMID 28558785, 2017). "Molecular based therapies targeting epidermal growth factor receptor (EGFR) mutants or ALK rearrangements were shown to improve the outcome within well-defined subgroups of non-squamous cell carcinoma patients." (PMID 26313362, 2015). "Like HPV-associated squamous cell carcinomas arising elsewhere, anal squamous cell carcinoma has been shown to have a high frequency of expression of EGFR; whether or not its expression correlates to anti-EGFR therapeutic benefit remains an area of active investigation." (PMID 26498363, 2015).